RN7SL197P (RNA, 7SL, cytoplasmic 197, pseudogene)
Gene: Miscellaneous RNA gene on chromosome 20 (49,721,949 to 49,722,247, forward strand). Ensembl gene ENSG00000276031.
Homologues: Orthologues: chimpanzee Metazoa_SRP (98% identical), macaque Metazoa_SRP (92% identical). Paralogues in human: RN7SL3 (86% identical), RN7SL1 (85% identical), RN7SL2 (84% identical), RN7SL45P (81% identical), RN7SL91P (81% identical), RN7SL336P (81% identical), RN7SL126P (80% identical), RN7SL220P (80% identical), RN7SL333P (80% identical), RN7SL493P (80% identical), RN7SL597P (80% identical), RN7SL664P (80% identical), and 700 more.